BECN1 (beclin 1)
Description:
Plays a central role in autophagy. Acts as a core subunit of the PI3K complex that mediates formation of phosphatidylinositol 3-phosphate; different complex forms are believed to play a role in multiple membrane trafficking pathways: PI3KC3-C1 is involved in initiation of autophagosomes and PI3KC3-C2 in maturation of autophagosomes and endocytosis. Involved in regulation of degradative endocytic trafficking and required for the abscission step in cytokinesis, probably in the context of PI3KC3-C2. Essential for the formation of PI3KC3-C2 but not PI3KC3-C1 PI3K complex forms. Involved in endocytosis. May play a role in antiviral host defense. Beclin-1-C 35 kDa localized to mitochondria can promote apoptosis; it induces the mitochondrial translocation of BAX and the release of proapoptotic factors. (Microbial infection) Protects against infection by a neurovirulent strain of Sindbis virus.
Synonyms: ATG6; VPS30; beclin1
Tractability: Small molecule: a structure with a bound ligand is known. Antibody: UniProt places it where antibodies can reach, with high confidence. PROTAC: UniProt records ubiquitination sites on it; ubiquitination databases record sites on it; its protein half-life has been measured.
Gene: Protein-coding gene on chromosome 17 (42,809,870 to 42,833,350, reverse strand). Ensembl gene ENSG00000126581.
Subcellular location: Cytoplasm; Golgi apparatus, trans-Golgi network membrane; Endosome membrane; Endoplasmic reticulum membrane; Mitochondrion membrane; Endosome; Cytoplasmic vesicle, autophagosome; Mitochondrion (Beclin-1-C 35 kDa); Nucleus; Mitochondrion (Beclin-1-C 37 kDa)
Subcellular location (Human Protein Atlas): Cytosol; Nuclear bodies
Pathways (Reactome):
Disease: Dengue virus modulates apoptosis; RSV-host interactions; SARS-CoV-2 activates/modulates innate and adaptive immune responses; Translation of Replicase and Assembly of the Replication Transcription Complex
Immune System: Antigen Presentation: Folding, assembly and peptide loading of class I MHC; ISG15 antiviral mechanism
Autophagy: Macroautophagy
Metabolism of proteins: Ub-specific processing proteases
Gene Ontology:
Molecular function: GTPase binding; molecular adaptor activity; phosphatidylinositol 3-kinase binding; protein binding; protein kinase binding; protein-macromolecule adaptor activity; ubiquitin protein ligase binding; identical protein binding
Biological process: autophagosome assembly; autophagosome maturation; autophagy; cytoplasmic pattern recognition receptor signaling pathway; early endosome to late endosome transport; mitophagy; mitotic metaphase chromosome alignment; negative regulation of programmed cell death; phosphatidylinositol-3-phosphate biosynthetic process; positive regulation of attachment of mitotic spindle microtubules to kinetochore; positive regulation of autophagy; positive regulation of intrinsic apoptotic signaling pathway; protein-containing complex assembly; receptor catabolic process; regulation of autophagy; regulation of cytokinesis; regulation of macroautophagy; response to mitochondrial depolarisation; cellular defense response; cellular response to glucose starvation; cellular response to nitrogen starvation; late endosome to vacuole transport; macroautophagy; negative regulation of apoptotic process; positive regulation of phosphatidylinositol 3-kinase/protein kinase B signal transduction; and 21 more
Cellular component: cytoplasm; cytoplasmic side of mitochondrial outer membrane; cytosol; endoplasmic reticulum; endoplasmic reticulum membrane; endosome; endosome membrane; mitochondrial membrane; mitochondrion; nuclear body; nucleus; phosphatidylinositol 3-kinase complex, class III; autophagosome; phosphatidylinositol 3-kinase complex, class III, type I; phosphatidylinositol 3-kinase complex, class III, type II; cytoplasmic vesicle; dendrite; Golgi apparatus; phagocytic vesicle; protein-containing complex; trans-Golgi network
Genetic constraint (gnomAD): Loss-of-function variants: 11 observed, 55.15 expected, observed/expected ratio (o/e) 0.2, 90% interval 0.12 to 0.33. The upper end of that interval is the gene's LOEUF score, 0.33, which puts it in group 1 of 6, group 1 being the genes least tolerant of losing a copy. Missense variants: 396 observed, 546 expected, observed/expected ratio (o/e) 0.73, 90% interval 0.67 to 0.79. Synonymous variants: 168 observed, 200.72 expected, observed/expected ratio (o/e) 0.84, 90% interval 0.74 to 0.95.
Homologues: Orthologues: chimpanzee BECN1 (99% identical), macaque BECN1 (99% identical), mouse Becn1 (98% identical), dog BECN1 (98% identical), rat Becn1 (97% identical), pig BECN1 (97% identical), guinea pig BECN1 (93% identical), tropical clawed frog becn1 (88% identical), zebrafish becn1 (78% identical), Drosophila melanogaster Atg6 (50% identical), Caenorhabditis elegans bec-1 (26% identical). Paralogues in human: BECN2 (54% identical).
Diseases named in the same sentence as BECN1 in open-access papers:
BECN1 is named in the same sentence as 468 diseases in open-access papers, as found by Europe PMC text mining. Sharing a sentence is not in itself a finding about the gene and the disease. The quoted sentences say what the papers report.
breast carcinoma (357 papers, 2010 to 2026). "In the first reports of the tumor‐suppressive role of autophagy, allelic loss of BECN1 was identified in breast cancer cells and primary tumor material." (PMID 39129390, 2025). "In fact, it has been reported that heterozygous Becn1-deficient mice are susceptible to liver cancer, lung cancer and lymphoma, and that a single allele of BECN1 is frequently deleted in breast cancer, ovarian cancer and prostate cancer." (PMID 39596291, 2024). "In our study, we highlighted the potential association of BECN1 expression in breast cancer with poor tumor differentiation denoting its possible link with disease aggressiveness." (PMID 38787424, 2024). "In breast cancer, BECN1 was found to exhibit loss of heterogeneity in 45% of breast cancer tissue, where deletion of one allele is observed." (PMID 38787424, 2024). "As one of the common malignancies in women, the development of breast cancer is also associated with autophagy, and Beclin-1 gene is a hot gene in both autophagy research and the breast cancer field." (PMID 38315272, 2024). "Studies have indicated that diminished autophagic processes are linked to tumor development, for example, low Beclin‐1 levels are observed in ovarian cancer, breast cancer, and prostate cancer." (PMID 39109577, 2024). "The role of HMGB1 in the cytoplasm is associated with BECN1-mediated autophagy, metastasis, and chemo- and radiotherapy resistance in breast cancer." (PMID 37190065, 2023). "Numerous studies in the area of breast cancer survivors on the METABRIC (Molecular Taxonomy of Breast Cancer International Consortium) dataset demonstrated that a lower expression of BECN1 is associated with a worse probability of survival." (PMID 37213283, 2023). "In a similar fashion, it was demonstrated that DNMT3B bonded to the BECN1 promoter, causing an increase in DNA methylation and a decrease in protein expression in tamoxifen-resistant breast cancer (MCF7/TAMR) cells." (PMID 37571432, 2023). "The lack of prominent autophagic response in TNBC cells is likely due to intrinsic autophagy deficiency caused by spontaneous monoalleilic deletion of Beclin 1 in breast cancer in general and low mRNA level of Beclin 1 in TNBC in particular." (PMID 37598181, 2023). "In vivo studies in mice indicate that loss of heterozygosity for BECN1 leads to an increased incidence of spontaneous carcinomas, including breast carcinomas with basal-like features." (PMID 36008963, 2022). "On the other hand, BECN1 (Beclin-1), an autophagy associated gene which play a role in autophagosome formation, are frequently deleted in some cancer, such as breast cancer, ovarian and prostate cancer." (PMID 35778432, 2022). "Evidence that mutations in ATG genes are associated with cancer was first provided when a monoallelic deletion in BECN1, an essential autophagy gene encoding Beclin 1, was shown to result in tumorigenesis in breast cancer." (PMID 35699756, 2022). "Clinical data further confirm that low BECN1 protein levels are associated with poor prognosis and rapid progression of breast cancer." (PMID 36008963, 2022). "LncRNA H19 depletion promoted the interaction between DNMT3B and Beclin 1 promoter, causing the Beclin 1 DNA methylation, decreasing tamoxifen resistance due to autophagy inhibition in breast cancer." (PMID 35620052, 2022). "Back in 1999, the Levine laboratory discovered that BECN1 was the mammalian ortholog of the yeast Vps30/Atg6, providing evidence of a rescued autophagy function both in Atg6-deficient yeast and in breast cancer cells (MCF7) expressing low BECN1 levels." (PMID 35832792, 2022). "For example, the autophagy gene Beclin 1 (ATG6) exhibits mono-allelic deficiency in 40–75% of sporadic human breast cancers and ovarian cancers, indicating that Beclin 1 is a tumor-suppressor gene." (PMID 36676047, 2022). "For example, BECN1 single allele deletion is commonly seen in breast cancer, ovarian cancer, and prostate cancer." (PMID 35719323, 2022).
breast carcinoma (continued). "As heterozygous disruption of Becn1 delays Palb2-associated mammary tumor development, we sought to further examine the role of autophagy in mammary tumor development following PALB2 loss." (PMID 35404932, 2022). "The present study provides further evidence of the significance of autophagy and Beclin-1 to cause cell death in the breast cancer cell line BT-20." (PMID 33507706, 2021). "HER2 is known to inhibit autophagy by binding to Beclin1, and HER2 amplification in breast cancer is often associated with BECN1 DNA copy loss." (PMID 34207792, 2021). "Recent reports stated that cancers, especially breast cancers, are associated with the mutation of autophagy marker, Beclin-1." (PMID 34402718, 2021). "In line, monoallelic loss of BECN1 is frequent in HER2+ breast cancers and predicts response to HER2-inhibitors (trastuzumab)." (PMID 32878084, 2020). "The mechanism underlying this effect is unclear, but treatment of HER2+ breast cancer cell lines with the tyrosine kinase inhibitor Lapatinib disrupts the HER2-Beclin 1 complex and induces autophagy." (PMID 33287140, 2020). "Monoallelic loss of beclin-1 gene in a mouse model of breast cancer led to increased signs of DNA damage and activity of repair systems, therefore increasing the chance for introduction of mutation and thus the risk of tumorigenesis." (PMID 33117715, 2020). "It is very important to notice that the monoallelic mutations of Beclin-1 gene have been frequently reported in prostate, ovarian, and breast cancers in humans." (PMID 33297472, 2020). "Reportedly, loss of Beclin-1 in cancer cells and Beclin 1 overexpression in stromal mesenchymal cells were closely linked to local recurrence and lymph node metastasis in breast cancer." (PMID 33425768, 2020). "In breast cancer, loss of BECN1 promotes mammary tumor development via regulation of WNT113, while it has also been demonstrated that BECN1 is essential for the tumorigenesis of breast cancer progenitor cells." (PMID 32358527, 2020). "Reportedly, loss and down-regulation of Beclin 1 expression was immunohistochemically observed in esophageal adenocarcinoma, colorectal cancer, breast cancer, but versa in pancreatic cancer." (PMID 33425768, 2020). "The BECN1 gene is rarely mutated in cancer; however, the mutation of BECN1 occurs in colorectal, gastric, breast, and prostate cancer due to the similar genomic proximity to the breast cancer susceptibility gene BRCA-1." (PMID 33375363, 2020). "A deletion of one allele of the Beclin-1 gene was observed in breast cancer and other estrogen-dependent malignancies: ovarian and prostate cancers." (PMID 29469819, 2017). "We here observed that high expression of EHMT2 was associated with the suppression of Beclin-1 in three independent and publicly available breast cancer datasets—TCGA, UNC, and NKI." (PMID 27174920, 2016). "Our previous study disclosed that loss of Beclin 1 nuclear positivity in malignant canine mammary tumors was associated with poor prognostic factors." (PMID 26506105, 2015). "Previously, a number of studies have documented that Beclin 1 expression is down-regulated in breast cancer, liver cancer, cervical and ovarian cancer, associating with an inferior prognosis." (PMID 24260370, 2013). "To this end we performed a GST pull-down between the C-terminal part of FYVE-CENT (residues 1807–2539) that contains the R1945Q mutation found in breast cancer cell lines and myc-Beclin 1 in HeLa cell lysates." (PMID 21455500, 2011).
breast carcinoma (continued). "Beclin 1 contains a leucine-rich nuclear export signal motif which when mutated prevents Beclin 1 from fulfilling its role in the cells nutrient deprivation-induced autophagy and tumor supressive functions in human breast carcinoma (MCF7) cells." (PMID 40971030, 2025). "BECN1 loss was frequently found in cell lines from breast cancer and material from mammary tumors." (PMID 38612567, 2024). "Consistently, monoallelic loss of BECN1 is often observed in human breast cancer cells." (PMID 37190065, 2023). "The pH-sensitive poly (β-amino ester) conjugated Beclin 1 peptides self-assemble into micelle-like nanoparticles (P-Bec1) and accumulate in lysosomes after cellular uptake; P-Bec1 causes lysosome damage and cell death in breast cancer cells." (PMID 36172279, 2022). "Based on the obtained results, we showed that 24 h exposure of human breast cancer cell lines to Les-3331 causes a decrease in Beclin-1 concentration in comparison with the control, where 7.965 ng/mL (MCF-7 cells) and 3.605 ng/mL (MDA-MB-231 cells) of Beclin-1 was detected." (PMID 35456915, 2022). "Interestingly, impaired autophagy, due to monoallelic loss of the essential autophagy gene Becn1, delayed and reduced Palb2-associated mammary tumorigenesis, suggesting that autophagy facilitates mammary tumor development following the loss of PALB2." (PMID 35404932, 2022). "The paradox of low BCL2 levels associated with a bad prognosis in breast cancer could be related to Beclin-1 inhibition." (PMID 33452364, 2021). "Likewise, improved clinical response to trastuzumab was observed in HER2+ breast cancer displaying loss of BECN1 gene." (PMID 33718194, 2021). "Also, Beclin-1 acts as a tumor suppressive that allelic loss of this gene can results in incidence of some types of cancer including prostate, ovarian, and breast cancer." (PMID 34660642, 2021). "HER2-positive breast cancer patients with allelic loss of BECN1 have worse clinical prognosis, suggesting that suppression of autophagy through this interaction may have pro-tumorigenic effects." (PMID 33224954, 2020). "Similarly, Palb2f/f; Wap-cre mice with monoallelic loss of BECN1 (BECN1±) experienced a significant delay in mammary tumor formation compared with mice homozygous in BECN1 expression." (PMID 33224954, 2020). "BECN1 is a haploinsufficient tumor suppressor and although it is not frequently mutated in cancers, Becn1+/− mice show an increased incidence of spontaneous tumors, including mammary carcinoma." (PMID 31877888, 2019). "A higher expression of Beclin 1 in healthy breast tissue than in breast cancer suggests a deficiency in cell-intrinsic autophagy in tumors, which could contribute to genomic instability during tumorigenesis." (PMID 29774126, 2018). "In fact, expression of the proautophagic protein Beclin 1 correlates with cancer prognosis where low levels are associated with a worse outcome in colorectal, pancreatic, gastric, and breast cancers and high levels of expression are associated with improved survival (95, –, 97)." (PMID 28174297, 2017). "A link between autophagy and HER2 expression has been described in a subset of human breast carcinomas: the loss of the autophagy regulator beclin 1 correlates with HER2 amplification while patients with beclin 1 gene responded better to Tz alone or in combination with other drugs." (PMID 26360292, 2015). "Moreover, the human chromosomal BECN1 locus (17q21) exhibits single-copy loss in prostate and breast cancers." (PMID 26239434, 2015). "40% of human breast carcinoma cell lines exhibit deletions of one or more alleles of beclin 1 gene." (PMID 21935420, 2011). "We determined whether BCL-W and BCL2 regulate ICI response in human breast cancer cells, and whether any effects involve changes in apoptosis and/or BECN1-associated autophagy." (PMID 20062536, 2010). "Whether there are other mechanisms for the loss of beclin 1 expression in breast cancer remains to be determined." (PMID 20230646, 2010).